TBC1D3C (TBC1 domain family member 3C)
Description:
Acts as a GTPase activating protein for RAB5. Does not act on RAB4 or RAB11 (By similarity).
Synonyms: MGC44903; PRC17; TBC1D3; TBC1D3A
Tractability: Antibody: UniProt places it where antibodies can reach, with medium confidence; its Gene Ontology location is reachable by antibodies, with medium confidence. PROTAC: UniProt records ubiquitination sites on it.
Gene: Protein-coding gene on chromosome 17 (38,057,693 to 38,068,634, reverse strand). Ensembl gene ENSG00000278299.
Subcellular location: Cell membrane
Subcellular location (Human Protein Atlas): Vesicles
Gene Ontology:
Molecular function: GTPase activator activity
Cellular component: endosome; membrane; plasma membrane
Homologues: Orthologues: chimpanzee TBC1D3B (97% identical). Paralogues in human: TBC1D3 (100% identical), TBC1D3D (99% identical), TBC1D3E (99% identical), TBC1D3F (99% identical), TBC1D3I (99% identical), TBC1D3K (99% identical), TBC1D3H (99% identical), TBC1D3L (99% identical), TBC1D3G (99% identical), TBC1D3B (99% identical), TBC1D26 (30% identical), USP6NL (29% identical), and 33 more.
Diseases named in the same sentence as TBC1D3C in open-access papers:
TBC1D3C is named in the same sentence as 2 diseases in open-access papers, as found by Europe PMC text mining. Sharing a sentence is not in itself a finding about the gene and the disease. The quoted sentences say what the papers report.
prostate carcinoma (1 paper, 2015). A carcinoma that arises from epithelial cells of the prostate gland. "TBC1D3C is a member of the TBC1D3 gene family, which has been linked to prostate cancer and tumour formation in mice." (PMID 26335491, 2015).
TBC1D3C also shares sentences with these, for which no sentence is quoted: tumour (1 paper).